IL1RL1 (interleukin 1 receptor like 1)
Diseases named in the same sentence as IL1RL1 in open-access papers (continued):
Sharing a sentence is not in itself a finding about the gene and the disease.
atopic asthma (3 papers, 2016 to 2022). An asthma that is characterized by symptoms that are triggered by an allergic reaction caused by inhaled allergens such as dust mite allergen, pet dander, pollen and mold. "IL1RL1, also known as ST2 which binds to IL-33, is associated with T2 inflammatory pathways and are upregulated in atopic asthma." (PMID 36076228, 2022).
myocardial infarction (3 papers, 2010 to 2020). Gross necrosis of the myocardium, as a result of interruption of the blood supply to the area, as in coronary thrombosis. "In vitro and animal model studies have demonstrated that IL33/IL1RL1 isoform A signaling protects cardiomyocytes from apoptosis by suppressing Caspase 3 activity and promoting the expression of anti-apoptotic proteins in vitro and improves survival in experimental myocardial infarction (MI) animals." (PMID 21629437, 2010).
myocarditis (3 papers, 2022 to 2023). Myocarditis is a condition that is characterized by inflammation of the heart muscle (myocardium). "Soluble interleukin 1 receptor-like 1 (sST2) is a novel predictor of poor outcomes, which is involved in inflammatory response and fibrosis of myocarditis." (PMID 37036563, 2023).
pancreatic cancer (3 papers, 2020 to 2024). "IL1RL1, also known as IL-33R/ST2, has been linked to tumor growth and progression in mouse models of pancreatic cancer." (PMID 33334063, 2020).
periodontitis (3 papers, 2023 to 2025). An acute or chronic inflammatory process that affects the tissues that surround and support the teeth. "This study investigated associations between single nucleotide variants (SNVs) in the IL33 gene and in the IL1RL1 (ST2) gene with periodontitis." (PMID 36947565, 2023). "Both the IL-33 gene and IL1RL1 gene (ST2 gene) have been implicated in the immune response in periodontitis, as well as in chronic disease of the airways, such as asthma." (PMID 36947565, 2023). "To identify the genes important for the periodontitis pathogenesis, we plotted the DEGs of the three tissues on a volcano plot and found that Il1rl1 was significantly altered in the PRT." (PMID 38548743, 2024). "Therefore, we induced periodontitis in both Il33Δ/Δ (generated by crossing Il33flox/flox mice with Actb-Cre mice) and Il1rl1–/– mice to determine whether signaling of the IL-33/ST2 axis or its modulation by a soluble decoy contributes to pathogenesis." (PMID 38548743, 2024).
breast tumor (2 papers, 2013 to 2016). "The effects of 1,25(OH)2D3 0.5nM on the expression of CYP24A1, DPP4, IL1RL1, CD14, CA2 and BMP6, were further explored in breast tumor derived cells, representing the epithelial and stromal compartments, using RT-qPCR." (PMID 23497279, 2013).
bronchiolitis (2 papers, 2012 to 2021). Inflammation of the bronchioles characterized by swelling of the bronchioles and mucus accumulation. "We hypothesized that IL1RL1 gene variants and soluble IL1RL1-a are associated with severe RSV bronchiolitis." (PMID 22574108, 2012). "We found a genetic link between rs1921622 IL1RL1 polymorphism and disease severity in RSV bronchiolitis." (PMID 22574108, 2012). "Furthermore, we examined soluble IL1RL1-a concentration in nasopharyngeal aspirates from children hospitalized with primary RSV bronchiolitis." (PMID 22574108, 2012).
chronic myeloid leukemia (2 papers, 2019 to 2025). "In the context of AML as well as chronic myeloid leukemia, the IL-33/IL1RL1 axis has been involved in only two reports." (PMID 40659660, 2025).
colorectal cancer (2 papers, 2019 to 2025). A primary or metastatic malignant neoplasm that affects the colon or rectum. "We previously showed that Il1rl1 expression on macrophages is associated with low CD8+ T cell cytotoxicity and inhibition of the IL-33/Il1rl1 pathway with an IL-33trap enhances antigen-specific T cell responses in vivo in colorectal cancer models." (PMID 40659660, 2025).
Crohn disease (2 papers, 2013 to 2015). A gastrointestinal disorder characterized by chronic inflammation involving all layers of the intestinal wall, noncaseating granulomas affecting the intestinal wall and regional lymph nodes, and transmural fibrosis. "Association of IL33 and IL1RL1 genes markers with Crohn’s disease (CD); case-control study." (PMID 23634226, 2013).
endometriosis (2 papers, 2019 to 2023). The growth of functional endometrial tissue in anatomic sites outside the uterine body. "Upregulation of IL1RL1, IL6ST, TNFRSF1B, and NR3C1 has been described in women with endometriosis." (PMID 38069001, 2023).
fibrosis (2 papers, 2021 to 2023). the formation of excess fibrous connective tissue in an organ or tissue in a reparative or reactive process. "Furthermore, increased IL1RL1 and decreased IFNGR1 expressions are confirmed in ILC2s from individuals with idiopathic PF, highlighting the applicability of Ifngr1-/-Rag2-/- mice as a mouse model for fibrosis research." (PMID 38097562, 2023).
gastric cancer (2 papers, 2024 to 2025). A primary or metastatic malignant neoplasm involving the stomach. "A synergistic partnership between IL-33/Il1rl1 and Wnt pathway through Bcl-xL drives gastric cancer stemness and metastasis." (PMID 40659660, 2025). "For example, EPHA3 interacts with the receptors for ephrin, promoting the migration of colorectal epithelial cells, whereas IL1RL1 is involved with the IL-33 receptor attracting gastric cancer cells." (PMID 39554905, 2024).
helminth infection (2 papers, 2016 to 2022). "A Th2 immune response is desirable in helminth infection, but as the ileum is not the site of infection, it was surprising to observe the up-regulation of genes, including CD86, Ovar-DRB1, IL1RL1 and IL-6, that polarize the immune response towards a Th2 response." (PMID 35576023, 2022).
lung adenocarcinoma (2 papers, 2017 to 2020). A carcinoma that arises from the lung and is characterized by the presence of malignant glandular epithelial cells. "IL1RL1 exhibited similar down-regulation in large cell lung carcinoma and lung adenocarcinoma." (PMID 31973134, 2020).
respiratory syncytial virus bronchiolitis (2 papers, 2012 to 2023). Bronciolitis caused by infection with respiratory syncytial virus. "In conclusion, our data demonstrate for the first time a genetic association between IL1RL1 and disease severity of RSV bronchiolitis." (PMID 22574108, 2012). "IL1RL1 SNP rs1921622 associated with severe RSV bronchiolitis." (PMID 22574108, 2012). "We studied the association between RSV and 3 selected IL1RL1 single-nucleotide polymorphisms rs1921622, rs11685480 or rs1420101 in 81 ventilated and 384 non-ventilated children under 1 year of age hospitalized with primary RSV bronchiolitis in comparison to 930 healthy controls." (PMID 22574108, 2012). "Subject characteristics of infants hospitalized for RSV bronchiolitis with IL1RL1-a measured in nasopharyngeal aspirate." (PMID 22574108, 2012). "The potential biological role of IL1RL1 in the pathogenesis of severe RSV bronchiolitis was further supported by high local concentrations of IL1RL1 in children with most severe disease." (PMID 22574108, 2012). "We further investigated our genetic finding of a potential role of IL1RL1 in severe RSV bronchiolitis by analyzing the relationship between local IL1RL1-a concentration and disease severity." (PMID 22574108, 2012). "In 207 hospitalized infants with RSV bronchiolitis, 20 ventilated and 187 non-ventilated, NPA was available to measure local IL1RL1-a levels." (PMID 22574108, 2012).
vasculitis (2 papers, 2014 to 2021). "The aim of the present study was to assess whether genetic variants at IL33 and IL1RL1, previously associated with immune-mediated diseases, are involved in the genetic predisposition to this vasculitis." (PMID 25409453, 2014). "In spite of an increased expression of the ST2 receptor was detected in the inflamed arteries of GCA patients, none of the tested IL1RL1 polymorphisms showed association with this vasculitis." (PMID 25409453, 2014).
viral infection (2 papers, 2016 to 2018). "The HP0RP3 highlights new poised genes such as Il1rl1 that codes for the receptor for the IL-33 alarmin that is produced by non hematopoietic cells during the course of viral infections and that plays an essential role in the development of anti-viral effector CD8 T cells." (PMID 27883012, 2016). "Interestingly, Il1rl1−/− mice were significantly protected from early weight loss after Cl-13 infection, suggesting that ST2 may be more important in the acute, rather than chronic, response to viral infection." (PMID 30515155, 2018).
AIDS (1 paper, 2018). A syndrome resulting from the acquired deficiency of cellular immunity caused by the human immunodeficiency virus (HIV). "According to hierarchal clustering analysis and KEGG network analysis, the proteins Interleukin-1 receptor-like 1 (IL1RL1, 10.62-fold) and thrombospondin 1 (THBS1, 1.82-fold) were differentially expressed in HIV/AIDS patients between the TM-positive group and the TM-negative control group." (PMID 30598657, 2018).
ankylosing spondylitis (1 paper, 2015). An autoimmune chronic inflammatory disorder characterized by inflammation in the vertebral joints of the spine and sacroiliac joints. "Regarding IL1RL1, a relevant role of IL1RL1 rs2058660, IL1RL1 rs2310173 and IL1RL1 rs13015714 in the development of several inflammatory conditions such as IBD and ankylosing spondylitis has been proposed." (PMID 26571131, 2015).
arterial disease (1 paper, 2022). "Our previous study reported that among patients with CAD and lower-extremity arterial disease, those with the IL1RL1 SNP rs950880 AA genotype tended to have lower sST2 levels and a lower survival rate." (PMID 35457109, 2022).
Autoimmunity (1 paper, 2023). The occurrence of an immune reaction against the organism's own cells or tissues. "IL1RL1+ Treg cells exert strong immunosuppressive and anti-inflammatory functions in wound healing, tissue homeostasis, autoimmunity, and cancer." (PMID 37611111, 2023).
basal cell carcinoma (1 paper, 2024). A carcinoma involving the basal cells. "Finally, there was suggestive evidence to support protective associations of genetically-proxied prothrombin concentrations with basal cell carcinoma and interleukin-1 receptor-like 1 concentrations with triple-negative breast cancer risk." (PMID 38301482, 2024).
cervical incompetence (1 paper, 2012). A clinical diagnosis presenting with painless cervical dilatation and spontaneous mid-trimester birth in recurrent pregnancies in the absence of spontaneous membrane rupture, bleeding or clinical chorioamnionitis. "Third, is IL1RL1 mRNA in maternal plasma involved in all clinical sub-groups of SPB (e.g. with or without preterm pre-labor rupture of membranes, cervical incompetence, antepartum hemorrhage)?" (PMID 22496790, 2012).
chronic heart failure (1 paper, 2020). "IL1RL1 codes for the receptor of IL-33, an important biomarker of myocardial stress, fibrosis, and chronic heart failure secreted in response to cell damage." (PMID 31924244, 2020).
Cognitive impairment (1 paper, 2025). Abnormal cognition is characterized by deficits in thinking, reasoning, or remembering. "Mouse models of AD have shown that IL-33/IL1RL1 signaling can alleviate cognitive impairment in AD by activating microglia to phagocytize amyloid beta." (PMID 40725187, 2025).
colon tumor (1 paper, 2021). "We found that the expression levels of some genes enriched in IL-11+ fibroblasts, including Wnt5a, Mmp13, Timp1, Il1rl1, Cxcl5, Saa3, Inhiba, Ascl4, and Tnfrsf11b, were elevated in mouse AOM/DSS-induced colon tumor tissues." (PMID 33863879, 2021).
cyst (1 paper, 2020). A sac-like closed membranous structure that may be empty or contain fluid or amorphous material. "We also detected an increased parasite burden in the brains of infected mice that lacked the IL-33 receptor (known as ST2 or il1rl1), by cyst count and quantitative PCR, demonstrating a role for extracellular IL-33 signaling during this infection." (PMID 33108405, 2020).
diabetic kidney disease (1 paper, 2023). Progressive kidney disorder caused by vascular damage to the glomerular capillaries, in patients with diabetes mellitus. "Based on the implication of IL-33 in diabetic kidney diseases, this observation warrants the inclusion of the IL-33/IL1RL1 axis in further investigations." (PMID 36672735, 2023).
diarrhoea (1 paper, 2022). "Some of the DEGs in diarrhoea-susceptible sheep, enriched in GO terms and sub-network analysis, included IL-6, LOC101121216 (serum amyloid A), SIGLEC1, CHI3L1, S100A9, CD14, CD68, CD86, Ovar-DRB1, IL1RL1, LOC101103238 (CXCL5), CCL22 and IL1RN." (PMID 35576023, 2022).
endothelial dysfunction (1 paper, 2024). In vascular diseases, endothelial dysfunction is a systemic pathological state of the endothelium (the inner lining of blood vessels) and can be broadly defined as an imbalance between vasodilating and vasoconstricting substances produced by (or acting on) the endothelium. "Moreover, interleukin-33 (IL-33) and interleukin 1 receptor-like 1 (IL-1RL1; sST2) are linked to endothelial dysfunction and therefore higher cardiovascular risk." (PMID 38673616, 2024).
experimental autoimmune encephalomyelitis (1 paper, 2023). An autoimmune demyelinating disease of the central nervous system that is produced experimentally in animals by the injection of homogenized brain or spinal cord in Freund's adjuvant. "Interleukin-1 receptor-like 1 (IL1R1) is an immune-related gene and has been involved in the pathology of multiple sclerosis and experimental autoimmune encephalomyelitis." (PMID 37061663, 2023).
fetal growth restriction (1 paper, 2012). A fetus that does not grow beyond the 10th percentile of conventionally accepted weight for gestational age. "Therefore, a decrease in NO production is directly linked to lowered expression of the receptor for IL-33 (IL1RL1) and could reflect a supporting causative factor in the etiology of fetal growth restriction." (PMID 22808055, 2012).
Flavivirus Infections (1 paper, 2023). Infections with viruses of the genus FLAVIVIRUS, family FLAVIVIRIDAE. "We therefore wondered if the survival defect observed in Il33-/- or Il1rl1-/- mice upon neuroinvasive flavivirus infection was due to altered T cell recruitment or activation." (PMID 37983247, 2023).
food allergy (1 paper, 2020). Gastrointestinal disturbances, skin eruptions, or shock due to allergic reactions to allergens in food. "In addition, IL-33 cytokine and receptor (IL1RL1, ST2) signaling is elevated in gastrointestinal allergic diseases, including food allergy and EoE." (PMID 33335529, 2020).
glioblastoma (1 paper, 2020). The most malignant astrocytic tumor (WHO grade IV). "In contrast, IL1RL1, TGFB2, GLI1, and EDNRB was over-expressed in classical, and desmoplastic medulloblastoma, and glioblastoma." (PMID 31973134, 2020).
gout (1 paper, 2015). A condition characterized by painful swelling of the joints, which is caused by deposition of urate crystals. "We therefore propose IL-33, IL-1RL1, IL-23R, and STAT4 as potential candidate susceptibility genes for gout." (PMID 26399911, 2015). "The current study therefore aimed to investigate the associations between the IL-33 rs3939286 A/G, IL-1RL1 rs13015714 G/T, IL-23R rs10889677 A/C, and STAT4 rs7574865 G/T single nucleotide polymorphisms (SNPs) and the risk of gout." (PMID 26399911, 2015). "The aim of this study was to investigate the associations between genetic variants in the interleukin (IL) and interleukin receptor (ILR) genes IL-33, IL-1RL1, IL-23R, and signal transducer and activator of transcription 4 (STAT4) and susceptibility to gout in Chinese Han male individuals." (PMID 26399911, 2015). "The production and function of cytokines may be affected by polymorphisms in the functional regions of their genes, suggesting that IL-33, IL-1RL1, IL-23R, and STAT4 may be candidate genes for the inflammatory pathogenesis of gout." (PMID 26399911, 2015). "The genetic distributions of rs3939286 in IL-33, rs13015714 in IL-1RL1, rs10889677 in IL-23R, and rs7574865 in STAT4 were detected in 1100 men with gout and 1227 ethnically matched controls, using Taqman allelic discrimination real-time polymerase chain reaction (PCR)." (PMID 26399911, 2015).
graft versus host disease (1 paper, 2022). An immune system disorder that occurs after allogeneic hematopoietic stem cell transplant and is a reaction of donor immune cells against host tissues. "Transcripts for the pro-inflammatory cytokine Il12A, a mediator of graft versus host disease, Il18 and its receptor, Il21r, and Il1rl1 were lower in NP over FAT cells." (PMID 36406265, 2022).
hyperuricemia (1 paper, 2020). An abnormally high level of uric acid. "For example, previous studies reported that gene polymorphism in Uygur Chinese may be correlated with hyperuricemia such as ApoE E4, IL-8, IL-1RL1, IL-18 and SLC17A1 genes." (PMID 32238146, 2020).
intestinal parasite infections (1 paper, 2019). "IL-33 has a single domain that binds to its receptor, IL-1 receptor like 1 (IL1RL1), also known as suppression of tumorigenicity 2 (ST2), and eliminates intestinal parasite infections through the induction of Th2 cytokines, such as IL-13 and IL-5." (PMID 30868311, 2019).
intestinal tumors (1 paper, 2022). "Moreover, data have shown that MSCs adjacent to intestinal tumors express IL1RL1 and interleukin 33, which can induce activation of tumor-promoting MSCs." (PMID 34971821, 2022).
leprosy (1 paper, 2021). Leprosy is a chronic infectious disease affecting primarily the skin and peripheral nervous system. "The IL18R1 gene is clustered with IL18RAP and IL1RL1 in the leprosy GWAS locus on chromosome 2q12.1." (PMID 34879060, 2021).
lymphedema (1 paper, 2025). Excess fluid collection in tissues, causing swelling. "In response to IL-33, the expression of Il1rl1 mRNA increased from POD 7, indicating that ST2-expressing cells infiltrated the lymphedema tissues." (PMID 39941140, 2025). "Therefore, since the increase in Il1rl1 indicates the induced infiltration of ST2+ cells, IL-33 may be involved in the infiltration of other ST2+ cells besides IL-13-expressing ILC2, leading to CD4+ T cell and Treg cell infiltration during lymphedema development." (PMID 39941140, 2025).
melanoma (1 paper, 2023). A malignant, usually aggressive tumor composed of atypical, neoplastic melanocytes. "In our experiments, we found higher expression levels of the IL1RL1 gene in melanoma cell lines with increased invasion after HHSEC-CM treatment, but we have not observed any IL-33 expression in the hepatic endothelial cells." (PMID 37240247, 2023).
meningioma (1 paper, 2023). A generally slow growing tumor attached to the dura mater. "In agreement, TRAF7-deficient MEFs also had an increased expression of several investigated TRAF7 meningioma signature genes, including IL1RL1, KRT16, KRT6A, and AQP3." (PMID 36937440, 2023). "Here, TRAF7 meningiomas expressed a high number of specific DEGs, including RAPGEFL1, KRT16, KRT6A, IL1RL1, NOS1, and others." (PMID 36937440, 2023).
nasal polyps (1 paper, 2022). "In this same study, genetic variation in IL1RL1 (rs1420101), which is the receptor for IL-33, failed to associate with CRS and nasal polyps." (PMID 36419128, 2022).
pancreatitis (1 paper, 2023). Inflammation of the pancreas. "Il33 is expressed during pancreatitis by a small subset (4%) of TFF1/ANXA10+Kras-mutant Gastric module-expressing epithelial cells and is predicted to initiate signaling to Tregs and ILCs (Module T8) by binding with its cognate receptor Il1rl1 and co-receptor Il1rap." (PMID 37167403, 2023).
renal fibrosis (1 paper, 2020). A final common manifestation of a wide variety of chronic kidney diseases characterized by glomerulosclerosis and tubulointerstitial fibrosis. "Our previous study reported that the deficiency of IL33 or IL1RL1 partially reversed the UUO-induced renal fibrosis." (PMID 32102434, 2020).